GNPDA2 (glucosamine-6-phosphate deaminase 2)
Description:
Catalyzes the reversible conversion of alpha-D-glucosamine 6-phosphate (GlcN-6P) into beta-D-fructose 6-phosphate (Fru-6P) and ammonium ion, a regulatory reaction step in de novo uridine diphosphate-N-acetyl-alpha-D-glucosamine (UDP-GlcNAc) biosynthesis via hexosamine pathway. Deamination is coupled to aldo-keto isomerization mediating the metabolic flux from UDP-GlcNAc toward Fru-6P. At high ammonium level can drive amination and isomerization of Fru-6P toward hexosamines and UDP-GlcNAc synthesis. Has a role in fine tuning the metabolic fluctuations of cytosolic UDP-GlcNAc and their effects on hyaluronan synthesis that occur during tissue remodeling.
Synonyms: GNP2; SB52
Tractability: PROTAC: ubiquitination databases record sites on it; its protein half-life has been measured.
Gene: Protein-coding gene on chromosome 4 (44,682,200 to 44,726,588, reverse strand). Ensembl gene ENSG00000163281.
Subcellular location: Cytoplasm
Subcellular location (Human Protein Atlas): Vesicles; Golgi apparatus
Pathways (Reactome):
Metabolism: Glycolysis
Gene Ontology:
Molecular function: glucosamine-6-phosphate deaminase activity; protein binding; identical protein binding
Biological process: UDP-N-acetylglucosamine biosynthetic process; glucosamine catabolic process; N-acetylglucosamine catabolic process; N-acetylneuraminate catabolic process; carbohydrate metabolic process; N-acetylglucosamine metabolic process
Cellular component: nucleus; cytoplasm; cytosol
Genetic constraint (gnomAD): Loss-of-function variants: 12 observed, 13.8 expected, observed/expected ratio (o/e) 0.87, 90% interval 0.56 to 1.41. The upper end of that interval is the gene's LOEUF score, 1.41, which puts it in group 5 of 6, group 1 being the genes least tolerant of losing a copy. Missense variants: 168 observed, 205.68 expected, observed/expected ratio (o/e) 0.82, 90% interval 0.72 to 0.93. Synonymous variants: 61 observed, 68.99 expected, observed/expected ratio (o/e) 0.88, 90% interval 0.72 to 1.09.
Homologues: Orthologues: chimpanzee GNPDA2 (100% identical), dog GNPDA2 (98% identical), guinea pig GNPDA2 (97% identical), mouse Gnpda2 (97% identical), pig GNPDA2 (97% identical), rabbit GNPDA2 (97% identical), macaque GNPDA2 (96% identical), rat Gnpda2 (96% identical), tropical clawed frog gnpda2 (93% identical), zebrafish gnpda2 (87% identical), Drosophila melanogaster Oscillin (74% identical), Caenorhabditis elegans T03F6.3 (65% identical). Paralogues in human: GNPDA1 (87% identical).